VHL (von Hippel-Lindau tumor suppressor)
Diseases named in the same sentence as VHL in open-access papers (continued):
Sharing a sentence is not in itself a finding about the gene and the disease.
cancer (continued). "Of note, metabolic reprogramming can affect each of these processes and the role of VHL/HIF axis in cancer metabolic reprogramming has been well defined." (PMID 33329393, 2020). "Then, we will dissect the underlying mechanisms in VHL/HIF axis-driven PPGL pathogenesis, with special attention paid to the interplay between the VHL/HIF axis and cancer cell metabolism." (PMID 33329393, 2020). "Hereditary PCC accounts for ~35% of cases and has been associated with germline mutations in several cancer susceptibility genes (e.g., KIF1B, SDHB, VHL, SDHD, RET)." (PMID 32354376, 2020). "These VHL-related cancers occur throughout the lifetime of the patient, requiring frequent intervention procedures, such as surgery, to remove the tumors." (PMID 33151962, 2020). "Distinct cancer cell lines (786+VHL, A549, ME180, U251, and HeLa) are characterized by different emission intensities of EYFP (controlled by minimal HIF-binding sites) at the same oxygen concentrations that correlate with total HIF-1α and HIF-2α levels." (PMID 32545356, 2020). "We set out to corroborate these data using a whole organismal vertebrate model, zebrafish, to overcome the limitation of the already transformed cancer cell lines for the functional studies for VHL." (PMID 32284789, 2020). "The spectrum of CDK6-specific PROTACs was extended to von Hippel Lindau (VHL) and cellular inhibitor of apoptosis protein 1 (cIAP1) that are essential for most cancer cells and therefore less likely to be inactivated." (PMID 33133483, 2020). "Here, we present our efforts to decipher the role of von Hippel-Lindau tumor suppressor protein (pVHL) in cancer insurgence." (PMID 30943211, 2019). "Gene networks of pVHL interactors built taking under consideration tissues developing cancer in VHL syndrome highlight an almost conserved core interaction network." (PMID 30943211, 2019). "The current evidence shows that RCC and PCa are Von Hippel-Lindau tumor suppressor (VHL)-related cancers." (PMID 31419966, 2019). "Amplification of the oncogenes ERBB2, CDK6, MDM2 affected dependency, as did point mutations in PIK3CA, KRAS, NRAS, VHL and BRAF, validating our approach to highlight genes with significance in cancer." (PMID 30803482, 2019). "STF-31 selectively inhibits the glucose transporter Glut1 and selectively impairs cell growth of kidney and other types of cancer cells that lack the von Hippel-Lindau (VHL) tumor suppressor protein." (PMID 31597342, 2019). "For the unlucky among the rest of us, that second hit in VHL will occur sufficiently quickly that a cancer will develop in middle age or beyond." (PMID 29656891, 2018). "In our hypothetical adipogenic metabolic evolution, ccRCC cancer cells undergoing tumourigenesis are in a sufficient energy state due to the VHL/HIF pathway." (PMID 29416602, 2018). "We also detected another five smRMGs that mutated in nearly half of the samples in corresponding cancers, including PCDHAC2 in SKCM (53%), ZFPM1 in ACC (52%), VHL in KIRC (49%), GNAQ in UVM (49%), and ADAM6 in LUSC (45%)." (PMID 30107644, 2018). "Our studies define a novel regulatory mechanism that operates upstream of VHL in cancer and provides additional insight into how its expression is extinguished in tumors that do not have inactivating mutations." (PMID 29053101, 2017).
cancer (continued). "Lower mRNA expression of VHL, HNF-4α and ALDH2 were found in cancer tissues compared to their corresponding adjacent tissues, and there was a positive correlation between VHL and HNF-4α mRNA and between HNF-4α and ALDH2 mRNA." (PMID 28643803, 2017). "It has been shown that in VHL-positive cancer cells, an overexpression of miR-28-5p reduced Mad2 levels, causing chromosomal instability." (PMID 29165391, 2017). "Together, these studies are the first to define an upstream mechanism regulating VHL protein turnover in cancer and describe the role of Daam2 in tumorigenesis." (PMID 29053101, 2017). "Together, these studies are the first to define an upstream mechanism regulating VHL suppression in cancer and describe the role of Daam2 in tumorigenesis." (PMID 29053101, 2017). "RPPA and bioinformatics approaches revealed that Daam2 expression is inversely correlated with a cohort of genes, including VHL, across a broad spectrum of cancers." (PMID 29053101, 2017). "Amongst the candidates identified in our RPPA screen, we chose to focus our studies on VHL because it’s a potent effector of tumorigenesis across many forms of cancer." (PMID 29053101, 2017). "Collectively, the results suggest that the VHL-aCS3 AdPROM results in complete proteolysis of endogenous SHP2 in multiple human cancer cell lines." (PMID 28490657, 2017). "RCC is known as a cancer that results from a genetic inactivation of the VHL tumor suppressor gene leading to an up-regulation of VEGF." (PMID 29074560, 2017). "Nevertheless, the upstream mechanisms that directly regulate VHL expression and protein turnover in cancer remain poorly defined." (PMID 29053101, 2017). "In some cancers, accumulation of HIF-1α can result from loss-of-function mutations in proteins that cause HIF-1α degradation, such as the Von Hippel-Lindau tumor suppressor (pVHL) or the enzymes that produce cofactors for the prolyl hydroxylases (PHDs)." (PMID 27058900, 2016). "To distinguish cancer vs. normal cells in subsequent experiments, we sequenced the VHL gene in a cohort of patients for whom cryopreserved viable single cell suspensions were available." (PMID 27422173, 2016). "RNA-seq revealed several HIF-1α-regulated genes that are upregulated in our VHL knockout cells and whose overexpression signifies an aggressive form of ccRCC in the cancer genome atlas (TCGA) database." (PMID 27358011, 2016). "While in CESC and KIRC, both of these two cancer types had their own high‐frequency mutations, such as MLL3, EP300, and VHL." (PMID 26992457, 2016). "Our results indicated that the aberrant expression of UCHL1 in cancer cells abrogated the VHL-mediated ubiquitination of HIF-1α, which led to the stabilization of HIF-1α and subsequent activation of HIF-1." (PMID 25615526, 2015). "Gene silencing by promoter region methylation of TSGs is a frequent mechanism described in human cancers, with epigenetic inactivation of VHL in ccRCC being one of the first examples." (PMID 28326264, 2015). "Validation of this notion would broaden the therapeutic appeal of GA as a treatment for VHL-positive cancers of the kidney and other tissues alike." (PMID 28326255, 2015). "We paid special attention to the HIF2α/VEGF signals since these two downstream targets of VHL have been reported to promote cancer progression via promoting angiogenesis and were two of the essential targets for the current therapies for advanced RCC." (PMID 26304926, 2015). "PCC, the other principal VHL-related cancer, is a rare catecholamine-secreting cancer originating in chromaffin cells of the adrenal gland." (PMID 25298778, 2014). "In fact, the only gene altered more frequently in this malignancy is VHL, a well-characterized driver of these cancers." (PMID 24622842, 2014). "We evaluated if gene CNL affects components of the VHL elongin BC protein complex in another cancer type characterized by inactivation of VHL: RCC." (PMID 25298778, 2014).
cancer (continued). "ACHN cancer cells are known to express a functional VHL, whereas Caki-2, 786-O, RCC4, and RCC10 cells express a mutated nonfunctional VHL protein." (PMID 24657971, 2014). "In other words, they theorized that hereditary forms of cancer, such as different manifestations of VHL, are the result of different and concomitantly compromised metabolic pathways." (PMID 24886840, 2014). "Our data suggest that VHL depression favors the selection of more aggressive cancer cells, which generate multifocal tumors." (PMID 25490036, 2014). "PLD also acts as a survival signal for cancers, such as renal cancer cells where PLD regulates hypoxia inducible factor 1α (HIF-1 α) at the translation level, in a vHL-independent fashion and promotes cancer cell proliferation." (PMID 24103483, 2014). "RCC is one of the top ten cancers incident in USA where VHL-gene alternations contribute to 75% of clear cell subtype of renal tumors, a major form of RCC." (PMID 23940778, 2013). "VHL protein is expressed in various normal and cancer tissues, where it is localized in the cytosol or membrane." (PMID 22390300, 2012). "VHL loss also causes abnormal activation of EGFR, a receptor tyrosine kinase whose uncurbed activity is oncogenic in many types of cancers." (PMID 21949687, 2011). "VHL and BRCA1 are also frequently mutated in cancer, but for other tumour suppressor genes, such as RASSF1A, promoter hypermethylation appears to be the principal mechanism for inactivation." (PMID 19285540, 2009). "Aberrant DNA methylation of CDKN2A has been observed in a wide range of common cancer types, while VHL and BRCA1 are silenced by methylation in a significant proportion of kidney and breast and ovarian cancers, respectively." (PMID 19285540, 2009). "The genes identified from the current analyses broaden the spectrum of VHL and hypoxia-responsive target genes to include many that have functions of interest to cancer biology." (PMID 15026807, 2004). "Our results suggest that therapeutic strategies designed to activate this pathway may represent a promising approach for treating cancers characterized by downregulated wild-type VHL and aberrant glucose metabolism." (PMID 41015595, 2025). "Cancer treatments targeting VHL aim to mitigate the oncogenic consequences of VHL dysfunction." (PMID 40576306, 2025). "We offer experimentally testable predictions about the context-dependent effects of TGF-β signaling on hypoxia-mediated EMT, as well as VHL loss on cancer hallmarks with or without secondary oncogene activation." (PMID 40238833, 2025). "It is evident from the data that genes such as VHL, TTN, BAP1, PBRM1, and SETD2 are consistently identified as the most frequently mutated genes in KIRC, underscoring their potential importance as key drivers of tumorigenesis in this specific cancer subtype." (PMID 40649942, 2025). "We offer experimentally testable predictions about the effect of VHL loss on cancer hallmarks, with or without secondary oncogene activation." (PMID 40238833, 2025). "The recent finding that ZHX2 is a VHL substrate that promotes ccRCC cancer progression by forming a complex with p65 to regulate NF-κB target genes let us to speculate that YAP may target the p65-ZHX2 signaling axis." (PMID 38979373, 2025). "There is no known pediatric cancer correlate of ccRCC for which VHL loss of function is a key tumorigenic event." (PMID 39510293, 2024). "In addition, we proposed several FDA-approved cancer-targeted drugs for various cancer types through PRISM drug screens, such as cabazitaxel for VHL-mutated kidney cancer and alectinib for lung cancer with NRAS or KRAS mutations." (PMID 37863651, 2024).
cancer (continued). "The VHL protein plays a central role in the regulation of HIFs, and its inhibition has emerged as a promising therapeutic approach in various pathological states, notably in specific cancers." (PMID 38257395, 2024). "Cancer mutations affecting the binding affinity of protein complexes were mostly observed in several key RCC drivers, such as VHL and TCEB1, while few deleterious missense mutations were observed in other RCC drivers, such as those involved in chromatin remodeling." (PMID 37964489, 2024). "Our efforts to uncover the precise mechanisms of VHL behind cancer immunotherapy could potentially lead to new therapeutic applications." (PMID 39050705, 2024). "This regulation of mRNA stability by VHL could have broad implications for gene expression and cellular processes, potentially influencing cell proliferation, survival, and other cancer-related pathways." (PMID 38618952, 2024). "VHL protein negatively controls angiogenesis, a critical factor in the progression of cancer." (PMID 36036061, 2023). "In the case of hypoxia or loss of VHL function, HIF is stabilized, which leads to the characteristic hypoxia response, including activation of genes involved in angiogenesis, invasion, metastasis, cancer stemness, and metabolic reprogramming." (PMID 37045834, 2023). "VHL has been shown to be aberrantly expressed in a number of human cancers." (PMID 36036061, 2023). "The most common alterations in this cancer are observed in the VHL/HIF pathway." (PMID 38273861, 2023). "In addition, through the transwell assay and cell proliferation assay, we found that VHL knockdown distinctly enhanced the inhibition of cell proliferation and invasiveness of Sunitinib to cancer cells." (PMID 37460463, 2023). "In 1993, the human VHL gene was mapped to chromosome 3p25 by genetic linkage studies performed on patients affected by a familial autosomal dominant syndrome characterized by several highly vascularized cancers." (PMID 37477829, 2023). "As sunitinib treatment is known to inhibit the proliferation of several cancer cell lines, we asked whether sunitinib can impact the healing ability of VHL-C162F cells by a scratch test of wound healing assay at high confluence at 24, 48, 72 and 96 h." (PMID 38201462, 2023). "In posttherapy HPD tumors, several somatic mutations were observed in known cancer genes that include tumor suppressor genes such as TSC2 and VHL, along with transcriptional upregulation of cancer signaling pathways, which include IGF-1, ERK/MAPK, and PI3K/AKT." (PMID 35399666, 2022). "No consistent associations with cancer-specific survival (CSS) have been found for VHL, PBRM1 and MTOR18–22." (PMID 35444164, 2022). "However, cancer cells can develop resistant mechanisms to PROTACs through mutation and/or downregulation of E3 ligase machinery corresponding to CRBN or VHL E3 ligase, based on which most PROTACs have been designed." (PMID 36140200, 2022). "Although our tertiary cancer centre has a specialized VHL outpatient clinic for patients with VHL disease, we only could include 7 patients in our prospective study, which is mainly related to the low prevalence of VHL disease." (PMID 36291853, 2022). "As an example, VHL gene mutation results in overproduction of HIF-1 (hypoxia-inducible factor 1), leading to the Warburg effect and other changes in metabolic processes in cancer cells." (PMID 35967759, 2022). "Evidence suggests that VHL-1 may modulate Akt activity as VHL-1 has been observed in cancer cells to suppress Akt kinase activity." (PMID 35886949, 2022). "Being a pan-cancer assay, VHL somatic mutations were not included in the NGS panel used in this study." (PMID 35974365, 2022). "Our previous study found that von-Hippel Lindau (VHL) gene mutation, the dominant reason for sporadic KIRC and hereditary kidney cancer- VHL syndrome, could affect VHL disease-related cancers development by inducing telomere shortening." (PMID 36189312, 2022).
cancer (continued). "Exploiting the genetic screening possible in C. elegans might provide further insight how mTOR influences phenotype and disease progression with VHL, and potentially reveal novel concepts to treat VHL-driven cancer." (PMID 34290272, 2021). "Cancers with transcription elongation defects display spurious transcription and defective mRNA processing of genes characterized by long genomic length; 48% of KIRC patients have mutations in VHL gene in the TCGA dataset." (PMID 34572448, 2021). "The VHL E3 ligase complex is a crucial target for cancer immunotherapy." (PMID 34943817, 2021). "The change was accompanied by a 5-fold decrease in the p-VHL in the patients with advanced cancers." (PMID 34563045, 2021). "The cancer dissemination was accompanied by an increase in both mRNA and VHL content." (PMID 34563045, 2021). "Further studies on each of these VHL-related cancers should be performed to uncover whether PSMA is overexpressed in these tumors." (PMID 34770976, 2021). "Also, SCG2 inhibited expression of HIF‐1α in cancer cells by interacting with VHL, a ubiquity‐degrading enzyme of HIF‐1α." (PMID 34160138, 2021). "VHL is described as a tumor suppressor gene and its inactivation may regulate cancer development and progression." (PMID 33321819, 2020). "As STATs are key transcription factors in cancer inflammation and immunity, the activation of STAT pathway due to the combined loss of VHL and PBRM1 could render the resulting tumors prone to immune regulation." (PMID 32743344, 2020). "However, dysregulated VHL/HIF axis plays a more important role in certain cancer types such as clear-cell RCC and PPGLs." (PMID 33329393, 2020). "Collectively, these data point to the existence of a signalling axis formed by VHL-EPOR/JAK/SOCS/STAT3 which may play important roles in supporting cancer cells proliferation." (PMID 32603638, 2020). "VHL and HIF1α positively and negatively, respectively, regulate ciliogenesis and cancer." (PMID 32825105, 2020). "It would be interesting to investigate whether the modulation of GHET1 for the interaction of VHL and HIF1α also occurs in other types of cancers." (PMID 30988076, 2019). "We propose that the protumorigenic role of HIF1α in VHL cancers may be blunted through drugs inhibiting mitochondrial respiratory complexes, such as metformin." (PMID 30728892, 2019). "There are clear examples with germline mutations in genes like adenomatous polyposis coli (APC), cadherin 1 (CDH1), BRCA1, von Hippel-Lindau tumor suppressor (VHL), and ataxia telangiectasia mutated (ATM) which are causative for the development of cancer in specific types of tissue." (PMID 31001323, 2019). "Besides NF-κB, there are AP-1, CEBP, and JunB, etc., which are involved in both inflammation and hypoxia/VHL-related cancer progression." (PMID 29562667, 2018). "Lastly, we will review the latest findings on targeting VHL signaling in cancer." (PMID 29562667, 2018). "As a substrate recognition unit of an E3 ubiquitin ligase complex, it remains to be determined as to whether there are VHL substrates regulating NF-κB pathway activity in cancer." (PMID 29562667, 2018). "It is an exciting time to study the multi-functionality of VHL in hypoxia signaling and cancer, which may yield additional therapeutic targets in cancer and other diseases." (PMID 29562667, 2018). "Moreover, when the cancer tissue samples were divided based on pathological staging, VHL expression and the level of 5hmC in the VHL promoter were both lower in pathological grade III tumors than in grades I or II." (PMID 28969028, 2017).